NUMB (NUMB endocytic adaptor protein)
Diseases named in the same sentence as NUMB in open-access papers (continued):
Sharing a sentence is not in itself a finding about the gene and the disease.
breast cancer (continued). "Interestingly, HNRNPL loss induces the exclusion of exon 12 in NUMB and the inclusion of exon 11 in EXOC1, suggesting a cooperative role of these two proteins in splicing regulation during breast cancer metastasis." (PMID 40323145, 2025). "Furthermore, NUMB could inhibit proliferation, invasion, and migration of breast cancer cells by adding with overexpressed NUMB lentivirus." (PMID 35478938, 2022). "The findings of current research demonstrated that breast cancer exosomes might further promote the migration and invasion of breast cancer cells when the NUMB expression levels were reduced, and the molecular mechanism of their regulation needs to be further investigated." (PMID 35478938, 2022). "ACBD3 reduces NOTCH signaling in conjunction with NUMB, but NUMB and NUMB-L are downregulated in breast cancers and NUMB-deficient breast cancer cells form increased cancer stem cell (CSC) pools, suggesting that ACBD3 may promote CSCs independently of NUMB." (PMID 36012147, 2022). "However, the NUMB expression in breast cancer cells treated with exosomes revealed a substantial decrease, indicating that the exosomes of breast cancer cells could inhibit NUMB expression." (PMID 35478938, 2022). "Further stratification of patient groups based on inverse Notch1/NUMB expression improved the predictive capability of NUMB for DDFS (p = 0.0004) in breast cancer patients (right), suggesting that NUMB may be another significant predictor of distant metastasis." (PMID 27506933, 2016). "For example, in breast cancer MDA-MB-468, and lung cancer A549 cell lines, overexpressing of Ex9sk NUMB isoform decreased colony number and/or suppressed cell growth whereas Ex9in overexpression exerted no change." (PMID 39863103, 2025). "In breast cancer cells treated with CHX, the half-life of the NUMB protein was significantly decreased in NOD1-overexpressing cancer cells." (PMID 38437016, 2024). "We observed that NOD1-overexpressing significantly inhibited NUMB protein expression and increased NICD1 levels in breast cancer cells." (PMID 38437016, 2024). "NOD1 was highly expressed on ALDH+ breast cancer stem cells (BCSCs) and cooperated with GAK to phosphorylate NUMB and promote its lysosomal degradation, thereby activating the NOTCH1-HEY1 signaling pathway to increase BCSCs." (PMID 38437016, 2024). "Compared with ER+ breast cancer, the mRNA levels of UBE2S and UBE2C were higher, while NUMB was reduced in ER− breast cancer." (PMID 36860312, 2023). "In mammary cancer, KRT19 was reported to interact with β-catenin/RAC1 complex and then upregulate NUMB expression, thus suppressing Notch signaling." (PMID 33767587, 2021). "To find the relevance of the NUMB, TCF7, and LEF1 promoters to β-catenin/RAC1, we performed a ChIP assay using anti-β-catenin/anti-RAC1 antibody in both colon and breast cancer chromatin samples." (PMID 30650643, 2019). "Our previous study showed that breast cancer properties were intensely upregulated upon KRT19 knockdown through the upregulation of Notch signaling, which was mediated by the Wnt/β-catenin/NUMB axis." (PMID 30650643, 2019). "We found several targets of QKI and RBFOX1, including FLNB, SLK, USO1, ENAH, ESYT2, NUMB and ARHGEF1, to be among the most differentially spliced genes in basal B breast cancer cell lines." (PMID 30059005, 2018). "Our results in this study suggest the possibility of using NUMB as a novel biomarker for prognosis and diagnosis of TNBC, as well as a potential candidate for targeted therapy of this highly aggressive breast cancer." (PMID 27506933, 2016). "In the present study, we report that NUMB is a negative regulator of EMT in both human mammary epithelial cells and breast cancer cells." (PMID 27506933, 2016). "Here, we report that NUMB is a negative regulator of EMT in both human mammary epithelial cells and breast cancer cells." (PMID 27506933, 2016).
breast cancer (continued). "Our data demonstrated that NUMB negatively regulates the EMT process in normal mammary epithelial cells and breast cancers." (PMID 27506933, 2016). "NUMB also functions as a tumor suppressor by abrogating Gli and/or NOTCH in glioblastoma and breast cancer." (PMID 24302991, 2013). "In breast cancer (BC), chemotherapy‐induced secretion of miR‐378a‐3p and miR‐378d in exosomes is significantly upregulated and acts on adjacent BC cells, silencing Dickkopf 3 and NUMB and activating the stemness pathways of WNT and NOTCH, allowing BC to become chemoresistant." (PMID 39247621, 2024). "First, we found that, in the RAB4A-high MDA-MB-231 breast cancer cells, NUMB expression is essentially absent and NOTCH1 and SOX2 expression are easily visualized by western blot." (PMID 39463384, 2024). "We also found that the Notch signaling inhibitory protein NUMB was downregulated in breast cancer upon KRT19 knockdown while no changes were observed in colon cancer." (PMID 30650643, 2019). "NUMB downregulation has been reported in breast cancer and non-small-cell lung carcinomas (NSCLCs), probably due to extensive degradation." (PMID 29721172, 2018). "Similar to NUMB, the EMT negative regulators GATA3 and FOXA1 had significantly lower expression in the BLBC subtypes, ER-negative and higher histological grade breast cancer patients, while the EMT inducers FOXC1, FOXC2 and SNAI1 mimicked the expression profiles of Notch1." (PMID 27506933, 2016). "Indeed, these proposed tumor suppressive functions of NUMB are consistent with previous studies conducted in breast cancer, non-small cell lung cancer (NSCLC), and salivary gland carcinomas in which tumors exhibited reduced expression of NUMB." (PMID 24980814, 2014). "To determine whether NOD1 increased breast cancer cell stemness by positively regulating BCSC symmetric division, we assessed the pattern of BCSC division in vitro by paired-cell analysis and immunostaining of the NUMB protein." (PMID 38437016, 2024). "The present study was aimed at figuring out whether exosomes have any effects on migration and invasion of breast cancer cells and whether NUMB protein produces any regulatory roles or not." (PMID 35478938, 2022). "The opposite effect in the expression of Notch signaling pathway-related proteins was also confirmed by Western blot in KRT19 knockdown cells, suggesting that NUMB might play an important role in the biased effect of KRT19 in Wnt/Notch signaling crosstalk in colon and breast cancer cells." (PMID 30650643, 2019). "Thus, NUMB transcriptional activity might play a pivotal role in the contrasting effects of KRT19 knockdown in colon and breast cancers." (PMID 30650643, 2019). "Similar to NUMB, the EMT negative regulators GATA3 and FOXA1 had significantly lower expression in the BLBC subtypes and in ER-negative and higher histological grade breast cancer patients, whereas the EMT inducers FOXC1, FOXC2 and SNAI1 mimicked the expression profile of Notch1." (PMID 27506933, 2016). "We examined the mechanisms by which NOD1 downregulated NUMB and observed that the mRNA expression level of NUMB was not affected by NOD1 in breast cancer cells." (PMID 38437016, 2024).
lung carcinoma (24 papers, 2013 to 2025). "We thus expanded the landscape of phenotypic associations to NUMB alternative splicing in lung cancer cell lines." (PMID 36304260, 2022). "Missense or truncating RBM10 mutations found in lung cancer patients were shown to disrupt RBM10-mediated splicing regulation of the Notch pathway regulator NUMB." (PMID 34065983, 2021). "It was observed that the down-regulation of NUMB suppressed cell growth and found to be associated with cancers like liver, leukemia and lung cancer." (PMID 28587194, 2017). "The only unexpected observation from this cell line RNA analysis was the high level of the NUMB exon 11 exclusion variant in the A549-LS cells, considering they are a lung cancer cell line." (PMID 25889998, 2015). "This expression correlates with preferential expression of the lung cancer-associated NUMB exon 11 inclusion variant." (PMID 25889998, 2015). "Functional analysis in lung cancer showed that tumor-associated increases in NUMB exon 9 inclusion correlated with reduced levels of NUMB protein expression and activation of the Notch signaling pathway, an event that has been linked to tumorigenesis." (PMID 24622401, 2014). "In breast and lung cancers, there is frequently loss of NUMB-mediated suppression of Notch signaling due to ubiquitination-induced degradation of all NUMB protein isoforms." (PMID 24722255, 2014). "It was recently observed that a novel point mutation at amino acid 354 of RBM10v1, replacing valine with glutamic acid, correlated with preferential expression of an exon 11 inclusion variant of the proliferation regulatory protein NUMB, which is upregulated in lung cancer." (PMID 25889998, 2015). "Secondly, in lung cancer there is preferential expression of the NUMB exon 11 inclusion variant." (PMID 25889998, 2015). "Finally, we show that 2-fold higher levels of the transcripts encoding the minus - compared to the plus - valine isoforms of both RBM10v1 and RBM10v2 correlates with higher levels of the lung cancer associated NUMB exon 11 inclusion variant, compared to the exon 11 exclusion variant." (PMID 25889998, 2015). "The assessment of NUMB expression in public array databases revealed a marked decrease in its expression of lung cancer." (PMID 40563292, 2025). "Based on several studies, the NUMB gene (NUMB Endocytic Adaptor Protein) (average methylation 51%, delta 20%, p = 0.005) acts as a tumor suppressor in lung carcinoma." (PMID 38791918, 2024). "In lung cancer, QKI (QKI-5) suppresses cancer-associated aberrant splicing of NUMB to prevent the activation of Notch signal and tumor proliferation." (PMID 38485986, 2024). "This is consistent with previous studies, which suggested that activated ERK signaling is a common mechanism that regulates NUMB isoform expression in breast and lung cancer cells." (PMID 36304260, 2022). "Based on these studies, NUMB has been proposed as a potential therapeutic target for tumorigenesis in several cancers, such as prostate, liver, breast and lung cancers." (PMID 27506933, 2016). "For example, NUMB expression is decreased in breast and lung cancer and NUMB is considered to be a tumor suppressor in these malignancies." (PMID 24550252, 2014). "In summary, our study demonstrates that QKI is a critical regulator of aberrant splicing in lung cancer and that the Notch signaling regulator, NUMB, is a key target of QKI in the control of cell proliferation." (PMID 24722255, 2014). "It is possible that the biologic effect of NUMB is isoform specific, as supported by a recent study which found that alternative splicing of NUMB produces functionally distinct protein isoforms that influence the proliferation of lung cancer cells differently." (PMID 24980814, 2014).
lung carcinoma (continued). "Protein quaking (QKI), a splicing factor frequently downregulated in lung cancer and correlated with poor prognosis, selectively suppressed the inclusion of NUMB mRNA exon 12 to promote the expression of a NUMB isoform, thereby inhibiting proliferation and the Notch signalling pathway." (PMID 33685397, 2021). "Interestingly, several other studies have indicated that QKI can also play tumour suppressive roles, and in one case, QKI‐directed alternative splicing of NUMB has been shown to reduce growth of lung cancer cells in vivo." (PMID 29871889, 2018). "Examples include BAP1 in cervical and lung cancer, CDK1 in bladder cancer, E2F2 in ovarian cancer, and RHOA, VEGF, NUMB, among others, in oral cancer." (PMID 41373532, 2025). "In lung cancer, the splicing factor QKI represses the inclusion of NUMB alternative exon through competing with a core splicing factor SF1, thereby inhibiting proliferation and Notch signaling." (PMID 36304260, 2022). "NUMB is the most studied downstream effector of RBM10, and dysregulation of NUMB AS is frequently found in lung cancer." (PMID 36335386, 2022). "It was recently reported that alternative NUMB exon 9 splicing led to differential expression of the NUMB-PRRS (p66) and NUMB-PRRL (p72) isoforms with opposite effects on the growth and colony formation of breast and lung cancer cells." (PMID 30726988, 2019). "Together, our data establish QKI as a critical regulator of splicing in lung cancer and present a new QKI/NUMB/Notch pathway in the regulation of cell proliferation." (PMID 24722255, 2014). "Similarly, changes in AS events in lung cancer will also affect the transcripts of VEGFA, MACF1, APP, and NUMB genes, thereby promoting the process of tumorigenesis." (PMID 36466711, 2022). "p72/p71 NUMB isoforms have been shown to be induced by RAS-ERK signaling in breast and lung cancer." (PMID 29507685, 2018). "Although this screening method has its limitations, it could be a useful strategy to discover drugs that counteract dysregulated mRNA splicing patterns in lung cancer, using a similar construct with a NSCLC-specific cassette exon, such as e.g., from the NUMB, ADD3, or caspase-9 genes." (PMID 34065983, 2021). "Studies have shown that in lung cancer, after aberrant splicing, the expression of BCL2L1, MDM2, MDM4, NUMB, and MET may play an important role in tumorigenesis, which may be due to the effects on cell apoptosis, cell proliferation, and intercellular cohesion‐related pathways." (PMID 33047900, 2020).
colorectal cancer (13 papers, 2016 to 2025). A primary or metastatic malignant neoplasm that affects the colon or rectum. "Additionally, NUMB has been implicated in colorectal cancer progression, where its loss is associated with increased EMT activity and Wnt pathway activation." (PMID 40296944, 2025). "NUMB functions as a cell fate determinant for stem cells, including cancer stem cells, and its aberrant expression plays a role in colorectal cancer and glioma stem cells." (PMID 38437016, 2024). "Specifically, miR-31, which targets NUMB, has been shown to promote carcinogenesis in colorectal cancer." (PMID 36672267, 2023). "miR-30a and miR-222 were demonstrated to target MIA3, while miR-146a-5p was reported to be suppressing NUMB expression in colorectal cancer cells." (PMID 36674525, 2023). "Other AS events in various genes, such as VEGFA, APP, and NUMB, have been reported to regulate the development of colorectal cancer and have demonstrated potential as new targets for the diagnosis, prognosis, and treatment of this type of malignancy." (PMID 31443718, 2019). "In colorectal cancer, it directs symmetric division by suppressing NUMB." (PMID 36672267, 2023). "Interference with the Snail–miR-146a–β-catenin loop by inhibiting MEK or Wnt activity reduces the symmetrical division of CRCSCs, attenuating the tumorigenicity, and the high-Snail–low-NUMB profile has been correlated with cetuximab resistance and a poorer prognosis in colorectal cancer." (PMID 36230757, 2022). "Therefore, they did not only confirm the role of the SNAIL/miR-146/Numb/β-catenin pathway in promoting SC properties, but also found a poor prognostic and treatment resistance correlation of SNAIL High NUMB Low in a group of patients with colorectal cancer in a clinical study." (PMID 36076302, 2022). "However, whether the MSI-2/NUMB pathway contributes to colorectal cancer (CRC) development in humans is still undetermined." (PMID 32984754, 2018). "miR-31-5p is highly expressed and functions as an oncogenic miRNA in colorectal cancer (CRC), and the negative regulation of miR-31-5p on NUMB results in increased proliferation, invasion, and migration of CRC cells." (PMID 38532427, 2024). "In colorectal cancer (CRC), CSC-derived exosomes promote the increase of CSCs via the transfer of the microRNA miR-146a-5p, which downregulates the expression of NUMB, a tumor suppressor gene regulating the Notch pathway." (PMID 31600881, 2019). "On the contrary, two other in vitro studies have shown that delivery of exosomal miR-30a, miR-222, and miR-146a-5p could promote colorectal cancer cell stemness by targeting two tumor-suppressor targets, namely, MIA3 and NUMB, respectively." (PMID 36674525, 2023). "The miR-146a–NUMB axis was demonstrated as being able to regulate the Wnt pathway in colorectal cancer stem cells (CRCSCs), rather than the Notch pathway, and inhibiting Wnt activity has a similar effect on MEK inhibition." (PMID 36230757, 2022).
non-small cell lung carcinoma (9 papers, 2014 to 2025). A group of at least three distinct histological types of lung cancer, including non-small cell squamous cell carcinoma, adenocarcinoma, and large cell carcinoma. "In human non-small-cell lung cancer, the gain-of-function mutation of the Notch1 gene and the weakening of the pathway due to the loss of NUMB have been described." (PMID 36644230, 2023). "Loss of NUMB expression has been found in salivary gland carcinoma, malignant pleural mesothelioma, breast tumors, non-small cell lung cancer and esophageal squamous cell carcinoma." (PMID 27506933, 2016). "There is also a significant inverse correlation between NOTCH1 and NUMB expression in non-small cell lung cancer (NSCLC)." (PMID 36672267, 2023). "(B) CD44 and NUMB exon peak plots relative to the AS analysis of the RNAseq data obtained from a previous ESRP1-KD study in human non-small cell lung cancer cells (H358) and from our own HCT116 and SW480 EpCAMhi/lo analysis." (PMID 36346211, 2022). "The AS events in MAFC1, ADD3 and NUMB were reported in the two recent researches in non-small cell lung cancer." (PMID 24622401, 2014). "They then went on to demonstrate, using an A549 non-small cell lung cancer (NSCLC) cell line with an RBM10v1(V354E) mutation (herein referred to as A549-JV), that expression of recombinant RBM10v1 protein, with either a valine or a glutamic acid at amino acid 354, altered NUMB splicing." (PMID 25889998, 2015). "Indeed, two independent studies, using unbiased exon arrays to identify alternative splicing events in non-small cell lung carcinoma (NSCLC) versus normal adjacent tissue, identified NUMB exon 9 inclusion as one of the most frequent tumor-associated splicing events." (PMID 39863103, 2025).